GFPT1 (glutamine--fructose-6-phosphate transaminase 1)
Diseases named in the same sentence as GFPT1 in open-access papers (continued):
Sharing a sentence is not in itself a finding about the gene and the disease.
tumor (39 papers, 2013 to 2025). "Elevated GFPT1 expression has been implicated in tumor growth, angiogenesis, metastasis, and resistance to chemotherapy." (PMID 39664728, 2024). "The positive association between GFPT1 and tumor progression, combined with its role in chemotherapy resistance, suggests that targeting GFPT1 could enhance the efficacy of current treatment strategies, particularly in patients with aggressive or advanced-stage disease." (PMID 39664728, 2024). "Specifically, GFPT1 has been identified as a key metabolic driver in PDAC cells and as a prognostic marker linked to tumor size in triple-negative breast cancer." (PMID 40830088, 2025). "Consistently, the translational levels of GFPT1 and O-GlcNAc were also enhanced in GC-resistant tumor tissues." (PMID 40740652, 2025). "Comparative analyses of GFPT isoform expression across diverse tumor types reveal that GFPT1 is broadly and constitutively expressed, while GFPT2 exhibits more restricted, tumor-specific expression patterns." (PMID 40830088, 2025). "Our analysis revealed that the GFPT1-High group exhibited significantly higher tumor purity, along with markedly lower stromal, immune, and ESTIMATE scores, suggesting reduced immune cell infiltration in this group." (PMID 39664728, 2024). "shRNA-mediated inhibition of GFPT1 led to a significant decrease in tumor growth and metastasis in vivo." (PMID 38732103, 2024). "To comprehensively analyze the expression and distribution of GFPT1 in various tumor tissues and adjacent normal tissues, we initially used the TIMER 2.0 tool to examine GFPT1 mRNA expression across multiple cancer types in the TCGA dataset." (PMID 39664728, 2024). "Three genes, HSPB1, HPRT1, and GFPT1, were found to be significantly upregulated in tumor samples compared to normal samples." (PMID 38875364, 2024). "Since the presence of hyaluronan was regarded as a major reason for the immune evasion of PDAC, abrogation of GFPT1 by DON increased the anti-tumor CD68+ macrophage and cytotoxic T cells, eventually sensitized anti-PD-1 immunotherapy effects." (PMID 36158580, 2022). "We analyzed public datasets to compare GFPT1 expression in tumor tissues and normal/adjacent pancreatic tissues." (PMID 33517899, 2021). "GFPT1 also plays an instrumental role in shaping the tumor immune microenvironment in PDAC, contributing to an immunosuppressive immune milieu, probably through modulating the extracellular matrix of cancer cells." (PMID 33517899, 2021). "In PDAC, activation of Kras supports anabolic glucose metabolism and tumor growth in mice depends on the expression of GFPT1." (PMID 23724116, 2013). "Although protein expression alone does not always equate to increased activity, elevated GFPT1 levels during nutrient stress have been correlated with tumor progression and poor patient prognosis, indicating that GFPT1 expression is crucial for its role in promoting cancer growth and survival." (PMID 40830088, 2025). "However, subsequent analyses indicated that GC treatment resulted in a substantial rise of GFPT1 in GC-resistant tumor tissues; however, GFPT1 expression was scarcely affected by GC treatment in GC-sensitive tissues." (PMID 40740652, 2025). "Notably, accumulating evidence indicates that GFPT1 is more closely associated with tumor growth and proliferation, whereas GFPT2 correlates with tumor metastasis and progression." (PMID 40830088, 2025). "In addition, GFPT1 expression in pre-chemotherapy biopsy tissues was also increased in GC-resistant tumor tissues, which can serve as an accurate early screening marker for predicting the sensitivity to GC therapy." (PMID 40740652, 2025). "However, significant changes were observed only between the NTC and GFPT1 groups when tumor weight was measured at the end of the experiment." (PMID 38732103, 2024). "In vivo data suggest that GFPT1 plays an important role in CRC tumor growth and metastasis." (PMID 38732103, 2024). "In PaCa, GFPT1 plays an important role in tumor progression." (PMID 38888874, 2024).
tumor (continued). "Additionally, higher GFPT1 protein expression was significantly associated with higher tumor grades in UCEC, and GFPT1 levels varied across different molecular subtypes of BRCA." (PMID 39664728, 2024). "GFPT1 expression was also increased in tumor tissue, consistent with its regulation by mutant KRAS." (PMID 34844667, 2021). "Since nodal involvement is a very significant process of tumor progression, it is helpful to know that GFPT1 may independently contribute to nodal metastasis." (PMID 33517899, 2021). "Additionally, GFPT1 expression was lower in LAML tumor tissues compared to normal controls." (PMID 39664728, 2024). "Overall, our pan-cancer analysis revealed increased GFPT1 mRNA and protein levels in BRCA, LIHC, and UCEC tumor tissues compared to normal tissues." (PMID 39664728, 2024). "The expression of FASN, GFPT1, OGT and O-GlcNAc is much higher in tumor tissues as compared to normal mucosa." (PMID 38732103, 2024). "Further analysis using the CPTAC database demonstrated a positive correlation between GFPT1 protein levels and advanced tumor stages in BRCA and UCEC, suggesting a potential link between GFPT1 and tumor progression." (PMID 39664728, 2024). "shRNA-mediated downregulation of GFPT1 and OGT inhibits cellular proliferation and the level of protein O-GlcNAcylation in vitro, and knockdown of GFPT1 leads to a significant decrease in tumor growth and metastasis in vivo." (PMID 38732103, 2024). "Importantly, knockdown of Gfpt1, the rate-limiting enzyme for HBP in PDAC cells, reduced total O-linked N-acetylglucosamine (O-GlcNAc) levels and tumor growth both in vitro and in vivo, supporting the essential role of HBP and protein glycosylation in PDAC tumor maintenance and growth." (PMID 36139512, 2022). "In support of this, expression analyses show that high GFPT2 levels are positively correlated with advanced tumor stages in multiple cancer types, a trend not observed for GFPT1." (PMID 40830088, 2025). "Our in vitro and in vivo studies suggest that targeting GFPT1 could be a potential therapeutic approach for CRC due to its significant role in cellular proliferation, tumor growth and metastasis." (PMID 38732103, 2024). "To examine the status of the HBP in human NSCLC, we assessed the expression level of its rate-limiting enzyme paralogs GFPT1 and GFPT2 using publicly available gene expression data of paired tumor-normal samples (LUAD n = 58; LUSC n = 52) from The Cancer Genome Atlas (TCGA)." (PMID 35396334, 2022). "Significant increases in GFPT1 expression were observed in DLBC, SKCM, and THYM tumor tissues, while no notable differences were found in ACC, LGG, OV, SARC, TGCT, or UCS samples." (PMID 39664728, 2024). "Similarly, another independent GSE3167 dataset also displayed the increased mRNA expression levels of GFPT1, PGM3, and UAP1 and the decreased GFPT2 level in tumor tissues, while the data of GNPNAT1 gene were not available in this dataset." (PMID 36158580, 2022).
cancer (31 papers, 2015 to 2025). A tumor composed of atypical neoplastic, often pleomorphic cells that invade other tissues. "This regulatory network positions GFPT1 as a key modulator in the interplay between nutrient sensing and oncogenic signaling, linking it to cancer growth and therapeutic resistance." (PMID 40830088, 2025). "In cancer, therapeutic strategies targeting GFPT1 primarily involve glutamine analogs that inhibit glutamine-utilizing amidotransferases." (PMID 40830088, 2025). "While studies in other cancers have primarily focused on GFPT1, the rate‐limiting enzyme of the HBP, the role of PGM3 has been largely overlooked." (PMID 40772310, 2025). "In cancer, the expression of GFPT1 and GFPT2 is differentially regulated under varying cellular stress conditions." (PMID 40830088, 2025). "Studies indicate that cancer cells upregulate GFPT1 to increase HBP flux, promoting abnormal protein O-GlcNAcylation." (PMID 40830088, 2025). "To further assess GFPT1 protein expression across different cancer types, we analyzed data from the CPTAC dataset." (PMID 39664728, 2024). "In agreement with published studies in other cancers, we show that pharmacological downregulation of both GFPT1 and OGT inhibits cellular proliferation." (PMID 38732103, 2024). "We developed a nomogram that integrates predictive factors such as age, cancer stage, T stage, N stage, and GFPT1 expression to quantitatively assess overall survival (OS) probabilities at 1, 3, and 5 years for BRCA patients." (PMID 39664728, 2024). "ShRNA-mediated downregulation of GFPT1 leads to a significant decrease in cancer cell lung colonization and growth." (PMID 38732103, 2024). "GFPT1 influences mRNA translation, cell cycle regulation, and M2 macrophage infiltration, thereby promoting cancer cell proliferation and metastasis." (PMID 39664728, 2024). "GFPT1 overexpression in return increases O-GlcNAcylation in cancer cells, and consequently promotes cancer cell proliferation, invasion and cancer stemness." (PMID 36158580, 2022). "Thus, targeting the GFPT1/HBP pathway appears a promising manner for promoting cell death in proliferating cancer cells experiencing nutrient stress." (PMID 40830088, 2025). "Overall, compounds targeting GFPT1 exhibit promising therapeutic potential in cancer management." (PMID 40830088, 2025). "Notably, GFPT1 has been implicated in interacting with PI3K/AKT/mTOR signaling, to impact the metabolic reprogramming associated with cancer as well as diabetic and cardiac diseases." (PMID 40830088, 2025). "The HBP is activated in a Kras-dependent manner in PDA via transcriptional regulation of Gfpt1, and it is similarly elevated in numerous cancers to provide a diverse set of functions, including the regulation of proliferation, survival, angiogenesis, and metastasis." (PMID 34951587, 2021). "A recent study suggested that inhibiting GFPT1 expression via pharmaceutical inhibitors or genetic silencing may result in reduced cell proliferation and cancer invasiveness." (PMID 33517899, 2021). "Furthermore, GFPT1 plays a significant role in promoting self-renewal and stemness of cancer cells." (PMID 40830088, 2025). "Targeted inhibition of GFPT1 and NR3C1 O-GlcNAcylation resensitizes the resistant cancer cells to chemotherapy in BCa orthotopic and xenograft mouse models." (PMID 40740652, 2025). "Metabolic remodeling enhances GFPT1-driven O-GlcNAcylation of key transcription factors, including NF-κB, HIFα, β-catenin, STAT3 and C-myc which play significant roles in cancer progression." (PMID 40830088, 2025). "Compared to the parental cancer cells, FASN, SCD1 and FADS2 expression at the mRNA and protein level consistently downregulated in the GFPT1 and OGT knockdown cells." (PMID 35844792, 2022). "GFPT1 was also found to induce the aggressive biology of PDAC by regulating self-renewal genes and by facilitating cancer cell invasion and migration." (PMID 33517899, 2021).
cancer (continued). "GFPT1/HBP functions as a coordinator of glucose and glutamine metabolism and is upregulated in various types of cancer." (PMID 33517899, 2021). "Hypoxic cancer cells have been shown to contain elevated levels of the HBP genes, including Gln–fructose-6-phosphate transaminase 1 (GFPT1) (which was overexpressed in our study) and GFPT2, and overall O-GlcNAcylation." (PMID 29615075, 2018). "The differential expression observed in cancer further suggests distinct biological functions for GFPT2 that are not redundant with those of GFPT1." (PMID 40830088, 2025). "It is important to note that these cancer-specific transcriptional biomarkers were not particularly unique at the genetic copy number level, apart from extensive copy number gains for GFPT1 in LUSC, and overall CNAs for TYMP in HNSC." (PMID 36831501, 2023). "Most importantly, we detected a novel GFPT1-ALK fusion that has not been reported in any type of cancer." (PMID 26295973, 2015). "While several factors currently limit its feasibility as a direct therapeutic target, the isoform-specific functions of GFPT1 and GFPT2 present an opportunity to develop cancer subtype-specific biomarkers and may inform the design of more selective therapeutic strategies." (PMID 40830088, 2025).
myopathy (5 papers, 2015 to 2025). A disease of the muscle in which the muscle fibers do not function properly. "Signifying its importance in striated myocytes are the reported myopathy in patients with Gfpt1 deficiencies, some of whom may have an associated cardiac feature." (PMID 34735873, 2021). "For example, the missplicing of exon 10 in the GFPT1 gene is a well-described biomarker for DM, but the same event is indeed present in all three myopathies analyzed here." (PMID 40149583, 2025).
metabolic disease (3 papers, 2022 to 2025). A congenital disorder (due to inherited enzyme abnormality) or acquired (due to failure of a metabolically important organ) disorder resulting from an abnormal metabolic process. "This work establishes a chronological paradigm of cholesterol sensing and identifies GFPT1 and ANGPTL4 as key regulators bridging glycosylation and lipid pathways, providing mechanistic insights into cholesterol-associated metabolic disorders." (PMID 40806239, 2025). "PPARA, PPARGC1A, and PPARGC1B, which are involved in the fatty acid oxidation of PLN-KO hiPSC-CMs, began to decline at day 30, while genes involved in glucose utilization, such as GNPNAT1, PGM3, and GFPT1, were upregulated, indicating that energy metabolism disorders began to occur." (PMID 35334215, 2022).
neuromuscular disease (2 papers, 2024 to 2025). "A total of 24 patients with GFPT1-CMS from 22 Han Chinese families across four neuromuscular disease centers were included in this study." (PMID 40442802, 2025). "Biallelic mutations to GFPT1 cause CMS, a rare neuromuscular disease characterized by fatigable muscle weakness." (PMID 39456185, 2024).
GFPT1 also shares sentences with these, for which no sentence is quoted: diabetes (5 papers); cardiac hypertrophy (4); Hyperglycemia (3); infection (3); lung adenocarcinoma (3); melanoma (3); adenovirus infection (2); bladder tumor (2); colon carcinoma (2); Lymph node metastasis (2); ovarian carcinoma (2); bone sarcoma (1); brain injury (1); bronchiectasis (1); cardiac ischemia (1); cardiomyopathy (1); cervical cancer (1); channelopathies (1); cholangiocarcinoma (1); chronic periodontitis (1); Cognitive impairment (1); esophageal squamous cell carcinoma (1); Fanconi anemia (1); heart failure (1); hepatitis B virus infection (1); hyperlipidemia (1); Intellectual disability (1); iron deficiency (1); limb girdle muscular dystrophy type 2A (1); malaria (1).
A further 18 diseases each share a sentence with GFPT1 in 1 paper.